PDGFRA (platelet derived growth factor receptor alpha)
Diseases named in the same sentence as PDGFRA in open-access papers (continued):
Sharing a sentence is not in itself a finding about the gene and the disease.
gastrointestinal stromal tumor (continued). "By performing a three-phased internal interlaboratory trial and conducting an external trial in Germany we were able to identify potential pitfalls when performing KIT and PDGFRA mutational analysis in gastrointestinal stromal tumors." (PMID 20598160, 2010). "Mutation analysis of KIT and PDGFRA genes in gastrointestinal stromal tumors is gaining increasing importance for prognosis of GISTs and for prediction of treatment response." (PMID 20598160, 2010). "This study was able to ascertain c-KIT and PDGFRA mutational status of seventeen of eighteen KIT positive canine gastrointestinal stromal tumors, representing a good amplification success rate of 94% from FFPE tissues." (PMID 20950418, 2010). "Gastrointestinal stromal tumours (GISTs) represent a heterogeneous group of tumours of mesenchymal origin characterized by gain-of-function mutations in KIT or PDGFRA of the type III receptor tyrosine kinase family." (PMID 19943934, 2009). "Gastrointestinal stromal tumours that are defined by a PDGFRA mutations occur almost exclusively in the gastric location, show epithelioid morphology and usually have a low mitotic count." (PMID 18253129, 2008). "Gastrointestinal stromal tumours that harbour different KIT or PDGFRA mutations have different molecular signatures at the level of gene expression, which further contributes to the complexity of GIST biology and variable response to treatment." (PMID 18253129, 2008). "Most gastrointestinal stromal tumors (GISTs) harbor c-KIT or PDGFRA mutations." (PMID 38992597, 2024). "Mutations in the c-KIT or PDGFRα genes primarily drive gastrointestinal stromal tumors (GISTs)." (PMID 39917203, 2024). "Gastrointestinal stromal tumors (GISTs), the most prevalent mesenchymal tumors of the gastrointestinal tract, are predominantlydriven by activating mutations in receptor tyrosine kinases such as c-Kit and PDGFRα." (PMID 39917220, 2024). "Gastrointestinal stromal tumors (GISTs) are typically characterized by activating mutations of the KIT proto-oncogene receptor tyrosine kinase (KIT) or platelet-derived growth factor receptor alpha (PDGFRA)." (PMID 38191907, 2024). "PDGFRA mutations are associated with gastrointestinal stromal tumors (GIST)." (PMID 37454137, 2023). "The most common mutations in gastrointestinal stromal tumors (GISTs) are KIT or PDGFRA mutations." (PMID 36612101, 2022). "Based on the recommendations of the Chinese consensus guidelines for the diagnosis and treatment of gastrointestinal stromal tumours, except for patients with PDGFRA exon 18 D842V mutation, exon 9 mutation, and wild-type GIST, the remaining patients received imatinib 400 mg/day adjuvant therapy." (PMID 36118766, 2022). "TKIs can effectively treat KIT or PDGFRA mutated gastrointestinal stromal tumors (GISTs)." (PMID 35685436, 2022). "Most gastrointestinal stromal tumors (GISTs) are driven by activating oncogenic mutations of receptor tyrosine kinase (RTK) KIT/PDGFRA, which provide a compelling therapeutic target, as evidenced by the clinical successes of KIT/PDGFRA-inhibition by small molecule therapeutics." (PMID 34025442, 2021). "In fact, PDGFRA mutations in gastrointestinal stromal tumors (GISTs) have been found to correlate with several noteworthy morphological features (i.e. epithelioid morphology of tumor cells and tumor-infiltrating mast cells) allowing histological discrimination from GISTs with c-kit mutations." (PMID 27738305, 2017). "Interestingly, the expression of PDGFRα in human ICLCs is in line with the observation that mutations in the PDGFRα gene cause gastro-intestinal stroma tumor (GIST), a tumor originating from interstitial cells of Cajal in the gastro-intestinal tract." (PMID 27764183, 2016). "PDGFRA mutations are often studied in gastrointestinal stromal tumor (GIST)." (PMID 27050078, 2016).
gastrointestinal stromal tumor (continued). "Gastrointestinal stromal tumours (GIST) are mainly characterised by the presence of activating mutations in either of the two receptor tyrosine kinases c-KIT or platelet-derived growth factor receptor-α (PDGFRα)." (PMID 25880691, 2015). "The best example for molecular targeted therapy in mesenchymal tumors is treatment with tyrosine kinase inhibitors in gastrointestinal stromal tumors (GIST) which carry activating KIT or PDGFRA (platelet derived growth factor receptor alpha) mutations in approximately 90%." (PMID 25844809, 2015). "The postulated relationship between KIT/PDGFRA mutations and their prognostic value in gastrointestinal stromal tumors (GISTs) has generated intense attention during the past decade, despite the fact that a great deal of studies have been conducted on this subject." (PMID 24674052, 2014). "Such PDGFRA mutations had previously only been found in gastrointestinal stromal tumors (GISTs)." (PMID 24307908, 2013). "Gastrointestinal stromal tumors (GISTs) in adults are generally driven by somatic gain-of-function mutations in KIT or PDGFRA, and biological therapies targeted to these receptor tyrosine kinases comprise part of the treatment regimen for metastatic and inoperable GISTs." (PMID 23730622, 2013). "Gastrointestinal stromal tumors (GISTs) have activating KIT or PDGFRA gene mutations." (PMID 23408993, 2013). "Heinrich and colleagues’ elegant study also identified PDGFRα-activating mutations in a subset of human gastrointestinal stromal tumors, for which PDGFRα may prove to be a useful molecular marker and therapeutic target." (PMID 23025904, 2012). "The most common PDGFRA alteration in gastrointestinal stromal tumors (GIST) is the exon 18 activation loop mutation D842V, which is resistant to imatinib and other type II TKIs but sensitive to type I TKI avapritinib." (PMID 42275235, 2026). "PDGFRA is also a validated target in other solid tumors, such as gastrointestinal stromal tumor (GIST), where PDGFRA‐D842V mutations confer high sensitivity to avapritinib (objective response rate (ORR) up to 91%)." (PMID 41036308, 2025). "The FDA has approved avapritinib as a treatment for adult patients with unresectable or metastatic gastrointestinal stromal tumor (GIST) that harbor a platelet-derived growth factor receptor alpha (PDGFRA) exon 18 mutation, including PDGFRA D842V mutations." (PMID 41216191, 2025). "Avapritinib is the only potent and selective inhibitor approved for the treatment of D842V-mutant gastrointestinal stromal tumors (GIST), the most common primary mutation of the platelet-derived growth factor receptor α (PDGFRA)." (PMID 38167404, 2024). "Exon 18 D842V, which is a point mutation from aspartic acid to valine at codon 842, is the most frequent mutation in Platelet-Derived Growth Factor Receptor alpha (PDGFRA)-mutated gastrointestinal stromal tumor (GIST)." (PMID 37027098, 2023). "Gastrointestinal stromal tumors (GIST) are rare mesenchymal tumors characterized by KIT or PDGFRA activating mutations." (PMID 37686582, 2023). "Avapritinib is indicated for the treatment of adults with metastatic gastrointestinal stromal tumors (GIST) harboring the PDGFRA D842V mutation; the drug is also used to treat systemic mastocytosis characterized by a KIT variant with the D816V mutation." (PMID 38202651, 2023). "The roles of this RTK in cancer have been extensively studied in the context of gastrointestinal stromal tumors (GIST) where activating point mutations on PDGFRA are found in 5–7% of GIST cases." (PMID 34716856, 2022). "On the other hand, imatinib is also a potent antagonist of c-kit receptor tyrosine (c-KIT) and PDGFRA kinases, both of which cause gastrointestinal stromal tumors (GIST)." (PMID 30836705, 2019). "Since KIT and PDGFRA mutations are observed in 85% of gastrointestinal stromal tumors (GISTs), it was also tested and approved for GIST treatment." (PMID 31480389, 2019).
gastrointestinal stromal tumor (continued). "Constitutive and ligand-derived signaling pathways mediated by KIT and PDGFRA mutated proteins found in gastrointestinal stromal tumors (GIST) were compared." (PMID 27872880, 2016). "Gastrointestinal stromal tumors (GIST) characteristically harbor in 85% of cases activating mutations in KIT or PDGFRA genes which encode a tyrosine kinase receptor." (PMID 27896638, 2016). "Gastrointestinal stromal tumors (GISTs) are characterized by mutations of KIT (v-kit Hardy-Zuckerman 4 feline sarcoma viral oncogene homolog) or PDGFRA (platelet-derived growth factor receptor α) that may be efficiently targeted by tyrosine kinase inhibitors (TKI)." (PMID 26867653, 2016). "Gastrointestinal stromal tumors (GIST) arise within the interstitial cell of Cajal (ICC) lineage due to activating KIT/PDGFRA mutations." (PMID 27793025, 2016). "Point mutations in the PDGFRα gene occur in about 5% of gastrointestinal stromal tumors (GIST); these mutations lead to amino acid residue replacements in critical regions of the receptor causing activation of the kinase." (PMID 24359404, 2013). "Given evidence that certain susceptibility loci and carcinogens are associated with characteristic mutations in other cancers, we hypothesized that these signature KIT or PDGFRA mutations may be similarly fundamental to understanding gastrointestinal stromal tumor etiology." (PMID 24159917, 2013). "In some of these cases a mutation in PDGFRA is found, leading to the diagnosis of gastrointestinal stromal tumor (GIST)." (PMID 24307908, 2013). "A subset of KIT/PDGFRA wild-type gastrointestinal stromal tumors (WT GIST) have been associated with alteration of the succinate dehydrogenase (SDH) complex II function." (PMID 22974104, 2012). "The non-recurrent translocation group tends to show complex genomic changes including gains/amplifications and deletions in multiple chromosomal regions, or activating mutations (e.g. KIT and PDGFRA) in gastrointestinal stromal tumors (GIST)." (PMID 23217126, 2012). "The majority of gastrointestinal stromal tumors (GIST) harbor gain-of-function mutations in KIT or PDGFRA, resulting in the activation of the downstream pathways PI3K/AKT, Ras/MAPK, and JAK/STAT3, and playing a crucial role in tumorigenesis." (PMID 22974104, 2012). "In support, in a family with a germline missense mutation of PDGFRA (G2675T) the mutated allele segregated with gastrointestinal stromal tumor (GIST) incidence." (PMID 22376240, 2012). "The tyrosine kinase inhibitor (TKI) imatinib targets KIT and PDGFRA, offering significant therapeutic benefits in advanced gastrointestinal stromal tumors (GISTs)." (PMID 40921853, 2025). "Beyond CML, imatinib demonstrated substantial clinical efficacy in gastrointestinal stromal tumors (GIST), which frequently harbor activating mutations in c-KIT or PDGFRA that lead to ligand-independent receptor activation and oncogenic signaling." (PMID 41302945, 2025). "What is the clinical role of positron emission tomography (PET) with 18F-fluorodeoxyglucose ([18F]FDG) in platelet-derived growth factor receptor α (PDGFRA)–mutant gastrointestinal stromal tumor (GIST), especially in the D842V-mutant subgroup?" (PMID 39853981, 2025). "Gastrointestinal stromal tumors (GISTs) are prevalent malignant mesenchymal tumors of the gastrointestinal tract, with most cases associated with mutations in the KIT or PDGFRA genes." (PMID 40129918, 2025). "In STS, however, actionable mutations are relatively rare, with the notable exception of KIT or PDGFRA alterations in gastrointestinal stromal tumors." (PMID 41228245, 2025). "Gastrointestinal stromal tumors (GISTs) arise from Cajal’s interstitial cell precursors and display a variety of genetic mutations, primarily in the KIT and PDGFRA genes." (PMID 39027749, 2024). "Most gastrointestinal stromal tumors (GISTs) are driven by activating mutations in KIT and PDGFRA or alterations in the succinate dehydrogenase (SDH) complex." (PMID 38730662, 2024).
gastrointestinal stromal tumor (continued). "While advanced gastrointestinal stromal tumors (GISTs) are primarily treated with tyrosine kinase inhibitors (TKIs), acquired resistance from specific mutations in KIT or PDGFRA frequently occurs." (PMID 39516322, 2024). "On the other hand, avapritinib has shown durable clinical efficacy in the treatment of gastrointestinal stromal tumors (GIST) with activating mutations in KIT and PDGFRα, which were previously considered untreatable due to resistance to TKI35." (PMID 38532028, 2024). "Beyond BCR::ABL1 mutations, genetic alterations have been critically evaluated for their role in conferring Imatinib resistance, especially in cancers like gastrointestinal stromal tumors (GISTs), where mutations in the KIT or PDGFRA genes are prevalent." (PMID 38607055, 2024). "Tyrosine kinase inhibitors are the standard treatment for gastrointestinal stromal tumours (GISTs) with oncogenic mutations in the KIT protooncogene (KIT) and the Platelet-Derived Growth Factor Receptor Alpha (PDGFRA) genes." (PMID 39796641, 2024). "For instance, sequencing of receptor tyrosine kinases (RTKs) like KIT and PDGFRA in gastrointestinal stromal tumors (GISTs) can guide the use of targeted therapies like imatinib." (PMID 38228904, 2024). "In gastrointestinal stromal tumors (GISTs), identifying prototypical mutations in the KIT/PDGFRA oncogenes, or in rare alternate genes, is essential for prognostication and predicting response to tyrosine kinase inhibitors." (PMID 39199677, 2024). "PDGFRA is mutated in about 6% of gastrointestinal stromal tumors (GIST)." (PMID 38532028, 2024). "Among soft-tissue cancers, this pathogenic variant is found in 12–20% of malignant peripheral nerve sheath tumors and estimated 3.5–13.5% of primary KIT/PDGFRA wild-type gastrointestinal stromal tumors." (PMID 39018206, 2024). "Oncogenic mutations in the stem cell factor receptor tyrosine kinase (cKIT) or the platelet-derived growth factor receptor alpha (PDGFRA) are found in 85–90% of patients with gastrointestinal stromal tumors (GISTs)." (PMID 36982486, 2023). "Mutations in KIT proto-oncogene, receptor tyrosine kinase (KIT) and platelet-derived growth factor receptor-α (PDGFRA) render the available tyrosine kinase inhibitors (TKI) ineffective in treating advanced gastrointestinal stromal tumors (GIST)." (PMID 37274264, 2023). "Resistance to the approved inhibitors of KIT proto-oncogene, receptor tyrosine kinase (KIT), and platelet-derived growth factor receptor α (PDGFRA) is a serious clinical challenge for patients with advanced gastrointestinal stromal tumors." (PMID 37046734, 2023). "For example, among the top three exclusively mutated gene pairs are BRAF and NRAS in skin cutaneous melanoma (p = 1.1 × 10–44), KIT and PDGFRA in gastrointestinal stromal tumour (p = 3.3 × 10–37), and EGFR and KRAS in lung adenocarcinoma (p = 6.6 × 10–29)." (PMID 37550388, 2023). "Gastrointestinal stromal tumour (GIST) is the most frequent soft tissue sarcoma and is characterised by activating mutations in the receptor tyrosine kinases KIT or PDGFRA." (PMID 37622176, 2023). "Moreover, we observed the same results in gastrointestinal stromal tumor (GIST) cell lines where a gain of function mutations on KIT or PDGFRA were the oncogenic drivers." (PMID 36834926, 2023). "Gastrointestinal stromal tumor (GIST) is a class of mesenchymal neoplasms of the digestive tract, and most of them possess an activated mutation of KIT or platelet-derived growth factor receptor alpha (PDGFRA)." (PMID 37675227, 2023). "A gastrointestinal stromal tumor (GIST) is a mesenchymal neoplasm of the gastrointestinal tract often known to express c-KIT or platelet-derived growth factor receptor alpha (PDGFRα)." (PMID 36874698, 2023). "The canonical mutations in gastrointestinal stromal tumors (GISTs) are typically activating mutations in KIT and platelet-derived growth factor receptor alpha (PDGFRA)." (PMID 35681640, 2022).
gastrointestinal stromal tumor (continued). "Conversely, the c-KIT mutation spectrum overlaps with those found in a gastrointestinal stromal tumor (GIST), and together with PDGFRA contribution (this case), a common mechanism of carcinogenesis is not excluded." (PMID 35621644, 2022). "Gastrointestinal stromal tumors (GISTs) are rare, mesenchymal tumors of the gastrointestinal tract, characterized by either KIT or PDGFRA mutation in about 85% of cases." (PMID 36142281, 2022). "Numerous studies have linked gastrointestinal stromal tumors to gene mutations in tyrosine kinase receptor (KIT) and platelet-derived growth factor receptor-alpha (PDGFRA)." (PMID 34991597, 2022). "Gastrointestinal stromal tumors (GISTs) are the most common mesenchymal tumors of the gastrointestinal tract, mostly driven by activating mutations in KIT or PDGFRα oncogenes." (PMID 35406604, 2022). "Familial gastrointestinal stromal tumor (GIST) is a rare autosomal dominant genetic disorder associated with KIT and PDGFRA germline mutations." (PMID 35320498, 2022). "In other cases, such as gastrointestinal stromal tumors (GIST), the identification of driver mutations in KIT and PDGFRα have effectively realized tailored therapies which radically changed tumor history." (PMID 34068344, 2021). "Several RTKs are clear examples of this context dependence: gastrointestinal stromal tumor mutations prefer IDR mutations in both KIT and PDGFRA, while leukaemia prefers catalytic site mutations in KIT." (PMID 33806614, 2021). "Gastrointestinal stromal tumors (GIST) is the most common mesenchymal tumor in the gastrointestinal tract, which is often caused by the mutation of KIT and PDGFRA genes." (PMID 34778339, 2021). "Gastrointestinal stromal tumors (GIST) are common mesenchymal tumors, and their effective treatment depends upon the mutational subtype of the KIT/PDGFRA genes." (PMID 34830948, 2021). "Succinate dehydrogenase deficient gastrointestinal stromal tumors (SDH-deficient GISTs), which lack KIT or PDGFRA mutations demonstrate unique clinical and pathological features, and they respond poorly to standard targeted therapy." (PMID 33612108, 2021). "Molecular analysis of KIT and PDGFRA is critical for tyrosine kinase inhibitor treatment selection of gastrointestinal stromal tumors (GISTs) and hence recommended by international guidelines." (PMID 33909171, 2021). "Over 85% of gastrointestinal stromal tumors (GIST) are driven by oncogenic mutations of the genes encoding KIT and/or platelet-derived growth factor receptor A (PDGFRA) receptor tyrosine kinases." (PMID 33740926, 2021). "Gastrointestinal stromal tumor (GIST) is the most common type of gastrointestinal mesenchymal tumor, primarily harboring gain of function mutations in the KIT or platelet-derived growth factor receptor-alpha (PDGFRA) genes." (PMID 34638938, 2021). "A noteworthy exception is represented by gastrointestinal stromal tumors, wherein activating mutations in either KIT or PDGFRα genes drives tumor proliferation." (PMID 34944915, 2021). "Management of gastrointestinal stromal tumors (GISTs) has been revolutionized by the identification of activating mutations in KIT and PDGFRA and clinical application of RTK inhibitors in advanced disease." (PMID 33320833, 2021). "Gastrointestinal stromal tumors (GISTs), the most common mesenchymal tumors of the gastrointestinal tract, are characterized by activating mutations in KIT or PDGFRA genes." (PMID 33212994, 2020). "Most gastrointestinal stromal tumors (GISTs) arise due to gain-of-function mutations of KIT and PDGFRA, encoding the receptor tyrosine kinase (RTK)." (PMID 33066449, 2020). "Platelet Derived Growth Factor Receptor Alpha (PDGFRA) mutations occur in only about 5–7% of gastrointestinal stromal tumors (GIST), and mainly involve the A-loop encoded by exon 18 (~5%), or more rarely the JM domain encoded by exon 12 (~1%), or the ATP binding domain encoded by exon 14 (<1%)." (PMID 32670260, 2020).